GPR18 (G protein-coupled receptor 18)
Description:
G protein-coupled receptor (GPCR) that plays a role in diverse physiological processes particularly within the immune and nervous systems. Becomes active when triggered by various endogenous ligands including endocannabinoid N-arachidonyl glycine (NAGly), delta-9-tetrahydrocannabinol or resolvin D2/RvD2 derived from the omega-3 fatty acid docosahexaenoic acid (DHA). Upon RvD2 binding, facilitates the resolution of inflammation, aiding in tissue repair and homeostasis. Mechanistically, RvD2 ligation initiates Galphas protein coupling, activation of cAMP-PKA signaling pathway and phosphorylation of STAT3, leading to RvD2-stimulated macrophage phagocytosis. Mediates NAGly-induced process of reorganization of actin filaments and induction of acrosomal exocytosis. Activation by N-arachidonoyl glycine (NAGly) can also induce apoptosis in macrophages (By similarity). Plays a role in homeostasis of CD8+ subsets of intraepithelial lymphocytes (IELs) (CD8alphaalpha and CD8alphabeta IELs) in small intestine by supporting preferential migration of CD8alphaalpha T-cells to intraepithelial compartment over lamina propria compartment, and by mediating their reconstitution into small intestine after bone marrow transplant (By similarity). Also participates in hypotensive responses, mediating reduction in intraocular and blood pressure (By similarity).
Synonyms: DRV2
Tractability: Small molecule: a high-quality ligand is known; it belongs to a druggable protein family. Antibody: UniProt places it where antibodies can reach, with high confidence; its Gene Ontology location is reachable by antibodies, with high confidence; UniProt predicts a signal peptide or a membrane-spanning region. PROTAC: a small molecule that binds it is known.
Target class: Family A G protein-coupled receptor; Membrane receptor
Gene: Protein-coding gene on chromosome 13 (99,254,732 to 99,261,744, reverse strand). Ensembl gene ENSG00000125245.
Subcellular location: Cell membrane; Cytoplasmic vesicle membrane
Pathways (Reactome):
Signal Transduction: Class A/1 (Rhodopsin-like receptors); G alpha (i) signalling events
Gene Ontology:
Molecular function: G protein-coupled receptor activity; protein binding
Biological process: G protein-coupled receptor signaling pathway
Cellular component: membrane; plasma membrane; cytoplasmic vesicle membrane
Genetic constraint (gnomAD): Loss-of-function variants: 21 observed, 24.42 expected, observed/expected ratio (o/e) 0.86, 90% interval 0.61 to 1.24. The upper end of that interval is the gene's LOEUF score, 1.24, which puts it in group 5 of 6, group 1 being the genes least tolerant of losing a copy. Missense variants: 379 observed, 432.89 expected, observed/expected ratio (o/e) 0.88, 90% interval 0.8 to 0.95. Synonymous variants: 160 observed, 163.19 expected, observed/expected ratio (o/e) 0.98, 90% interval 0.86 to 1.12.
Homologues: Orthologues: chimpanzee GPR18 (100% identical), pig GPR18 (91% identical), dog GPR18 (90% identical), macaque GPR18 (89% identical), guinea pig GPR18 (88% identical), rabbit GPR18 (87% identical), mouse Gpr18 (86% identical), rat Gpr18 (85% identical), tropical clawed frog gpr18 (66% identical), zebrafish gpr18 (61% identical), Caenorhabditis elegans gnrr-4 (17% identical). Paralogues in human: GPR17 (29% identical), CYSLTR1 (26% identical), F2RL1 (26% identical), LPAR4 (25% identical), LPAR6 (25% identical), F2R (25% identical), CYSLTR2 (24% identical), F2RL3 (24% identical), P2RY10 (24% identical), F2RL2 (23% identical), GPR20 (23% identical), GPR4 (23% identical), and 4 more.
Diseases named in the same sentence as GPR18 in open-access papers:
GPR18 is named in the same sentence as 68 diseases in open-access papers, as found by Europe PMC text mining. Sharing a sentence is not in itself a finding about the gene and the disease. The quoted sentences say what the papers report.
Sepsis (9 papers, 2016 to 2025). Sepsis is defined as life-threatening organ dysfunction caused by a dysregulated host response to infection. "The clinical relevance of SPM receptors is further supported by findings that reduced GPR18 expression on neutrophils predicts poorer sepsis outcomes." (PMID 40799817, 2025). "Elevations in GPR18, a G-protein-coupled receptor found on immune cells and most abundantly in the spleen, has only recently been considered a marker of late sepsis." (PMID 38255280, 2024). "In sepsis patients, elevated GPR18 expression on monocytes is correlated with a worse sepsis severity score." (PMID 38255280, 2024). "More recently, the transmembrane protein GPR18 has been identified as a potential biomarker of sepsis-induced immunosuppression." (PMID 38255280, 2024). "A decrease in the positive rate of GPR18 in neutrophils often predicts more severe sepsis and a poorer prognosis." (PMID 34484417, 2021). "Taken together, these data provide evidence that GPR18 expression in different cell types may provide a way of “fine tuning” biomarkers in sepsis." (PMID 38255280, 2024). "Interestingly, low GPR18 expression on neutrophils is correlated with increased severity and a worse prognosis due to sepsis." (PMID 38255280, 2024). "CXCR3, CCR7, HLA-DMA, and GPR18 might be correlated with the sepsis mechanism." (PMID 34484417, 2021). "CXCR3, CCR7, HLA-DMA, and GPR18 might participate in the mechanism of CAP with sepsis." (PMID 34484417, 2021). "Early recognition of late-sepsis biomarkers, such as decreased lymphocyte count, increased MDSC production, increased IL-10 levels, changes in GPR18 expression, and decreased HLA-DR expression, will help with targeted diagnoses and treatments." (PMID 38255280, 2024). "Through searching the sepsis-related publication of the key genes, CCR7, CXCR3, FYN, CEACAM1, CD81, AMPH, HLA-DMA, and G protein-coupled receptors (GPR18) were considered to be key genes." (PMID 34484417, 2021). "In human sepsis, survivors had a higher percentage of GPR18-positive peripheral blood neutrophils compared to non-survivors, suggesting that DRV2/GPR18 expression levels are associated with disease severity." (PMID 35508275, 2022). "Finally, in a model for sepsis induced by coeliac ligation puncture, the RvD2-DRV2/GPR18 pathway demonstrated protective effects by means of enhanced phosphorylation of ERK-1/2 in macrophages and an increase in phagocytosis." (PMID 30487747, 2018).
breast carcinoma (8 papers, 2013 to 2022). "For the Caldas early breast cancer cohort, GPR18-high patients showed much improved OS (undefined; median OS has not yet been reached) vs. 145 months." (PMID 32398659, 2020). "GPR18 is highly abundant in testes, spleen, and within the brain, and its mRNA was evident in detectable amounts in cell lines of a few tumor entities, including melanoma, breast cancer, and GBM." (PMID 33802282, 2021). "In our study, we show that GPR18, just as for GPR55, contributes to the effects of cannabinoids observed on paclitaxel-resistant breast cancer cell viability." (PMID 31611800, 2019). "However, the 7 genes matching this description (Clasrp, Cyp3a44, Gpr18, Lrp2, Map1b, Spen, and Ttn), are neither known breast cancer or pan‐cancer driver genes nor directly involved with the activation of MAPK/ERK signaling." (PMID 35398967, 2022).
melanoma (6 papers, 2014 to 2021). A malignant, usually aggressive tumor composed of atypical, neoplastic melanocytes. "Further studies are therefore invited to explore if, as a partial agonist, AM251 can GPR18-dependently exert anti-melanoma activity." (PMID 30845666, 2019). "First, we identified the presence of CB1, CB2(A), GPR18 (transcriptional variant 1) and GPR55 receptors in brain endothelial cells, while melanoma cells expressed CB1, CB2(A), GPR18 (transcriptional variants 1 and 2), GPR55 and GPR119." (PMID 24815068, 2014). "Importantly, siRNA-mediated silencing of GPR18 induced apoptosis in the human lymph node metastasis-derived Cmel 0709 melanoma cell line." (PMID 30845666, 2019). "Expression of CB1, CB2, GPR18, GPR55 and GPR119 were identified in A2058 human amelanotic melanoma cell line." (PMID 30845666, 2019). "Since besides CB1 and GPR55, AM251 can also target GPR18, one might speculate that modulating activity of this receptor may be responsible for the beneficial effects, especially, since GPR18 (as well as GPR119) was found to be overexpressed at the mRNA level in melanomas as compared to nevi." (PMID 30845666, 2019).
Obesity (6 papers, 2017 to 2025). Accumulation of substantial excess body fat. "Since some researchers suggest the possible role of GPR18 in the progression of metabolic disease and obesity, this receptor and its ligands became a new potential therapeutic target." (PMID 33809564, 2021). "GPR18 is also regulated by dietary fats, undergoing an early reduction, then increasing at middle obesity (8 weeks) and finally reducing again at late obesity (16 weeks)." (PMID 28086928, 2017). "GPR18 has been proposed to play a role in the progression of metabolic disease and obesity." (PMID 33809564, 2021). "The presented preliminary data support the idea that the search for selective GPR18 antagonists for the treatment of obesity might be promising." (PMID 33809564, 2021). "O-1602 and O-1918 are atypical cannabinoid ligands for GPR55 and GPR18, which may be novel pharmaceuticals for the treatment of obesity by targeting energy homeostasis regulation in skeletal muscle." (PMID 32824681, 2020). "Currently, the expression of GPR18 in the skeletal muscle and thus its role, if any, in obesity is unknown." (PMID 32824681, 2020). "GPR18 is expressed in DIO rat skeletal muscle and future work could focus on selectively modulating GPR18 in a tissue-specific manner, which may be beneficial for obesity-targeted therapies." (PMID 32824681, 2020). "Moreover, the expressions and distributions of GPR18 were evaluated in the hypothalamus neurons on diet induced obesity." (PMID 29439730, 2018). "Thus, the presented preliminary data support the idea that selective GPR18 antagonism represents a promising avenue for the further research, and that the development of selective GPR18 antagonists for the treatment of obesity might result in valuable and promising outcomes." (PMID 33809564, 2021). "Our data suggests that GPR18 has a role in skeletal muscle metabolism, just like the traditional cannabinoid receptors CB1 and CB2, and the other putative cannabinoid receptor GPR55, all of which have previously been shown to be expressed in skeletal muscle and all of which have a role in obesity." (PMID 32824681, 2020).
colitis (5 papers, 2016 to 2024). Inflammation of the colon. "Colon biopsies from patients with CD and UC and colon tissue from mouse colitis models showed higher levels of GPR18 transcripts compared to healthy controls in the microarray expression data." (PMID 38542895, 2024). "Gpr18 expression was increased in the colon in the DSS model of colitis, a model that depends on innate immune responses." (PMID 36389671, 2022). "We investigated the role of GPR18 in two mouse colitis models, the DSS and the T cell transfer model." (PMID 36389671, 2022). "GPR18 is a strong candidate involved in the mechanism by which Abn-CBD improves the outcome of colitis, since attenuation of TNBS-induced colitis by Abn-CBD was not reversed by CB1/CB2 antagonists on a macroscopic level." (PMID 27418880, 2016). "We investigated the role of GPR18 in a second mouse colitis model, in this case initiated by adaptive immunity, because the effect could be model-dependent." (PMID 36389671, 2022). "Therefore, we tested if GPR18 expression by cells other than T lymphocytes, including innate immune cells in the Rag1-/- hosts, was required for colitis." (PMID 36389671, 2022). "Like GPR183, GPR18 transcripts increased in microarray expression data from colon biopsies of UC and Crohn’s disease patients versus healthy controls and in colon tissue from mouse models of colitis." (PMID 36389671, 2022). "Despite low expression of GPR18 on lymphocytes, increased expression by other cell types could play a role in colitis pathogenesis, and therefore we tested a role for GPR18 in models of colitis dependent on innate immunity (DSS) and on adaptive immunity (T cell transfer model)." (PMID 36389671, 2022). "Another Gpr18 synthetic analog, PSB-KK-145, was shown to reduce inflammatory markers and signs of pain in models of colitis." (PMID 37645248, 2023). "We also studied the roles of GPR18 and GPR183 in the T cell transfer model and GPR18 in the DSS model of colitis." (PMID 36389671, 2022). "In summary, the data indicate that GPR18 does not play a nonredundant role in the DSS-induced model of colitis." (PMID 36389671, 2022). "Taken together, GPR18 expression by T lymphocytes is not required for the transfer model of colitis." (PMID 36389671, 2022). "Although the expression of GPR18 does not affect the course of colitis in mice, a possible ligand interaction with this receptor may play a role in inflammation regulation." (PMID 38542895, 2024). "We found that GPR18 expression is not essential for influencing disease severity of colitis in mice, when its expression was deleted in all cell types in the DSS model, or in the transfer model when either T cell expression or expression in other cell types was eliminated." (PMID 36389671, 2022). "Therefore, although Gpr18 expression was increased in the colon in colitis patients and in two mouse models of colitis, expression of GPR18, like as for GPR183, does not play a role in regulating disease severity." (PMID 36389671, 2022). "Similarly, lack of GPR18 expression in T cells or other cell types did not affect colitis pathogenesis in the T cell transfer or in the dextran sulfate sodium model." (PMID 36389671, 2022).
glaucoma (3 papers, 2016 to 2022). Increased pressure in the eyeball due to obstruction of the outflow of aqueous humor. "Cannabicitran does not interact with cannabinoid receptors, and the activity was associated with the activation of GPR18 (NAGly receptor), an important target for glaucoma." (PMID 36008978, 2022). "Based on the observation that the activation of GPR18 lowers the intraocular pressure in mice, GPR18 agonists have been proposed for the treatment of glaucoma." (PMID 32365486, 2020).
inflammatory bowel disease (3 papers, 2015 to 2025). A spectrum of small and large bowel inflammatory diseases of unknown etiology. "A recent genome-wide association study identified a polymorphism near the Gpr18 locus linked to inflammatory bowel disease." (PMID 26197390, 2015). "Our findings may also prove significant for understanding the GPR18 SNPs detected as being enriched in inflammatory bowel disease patients in genome-wide association studies." (PMID 29670628, 2018).
periodontitis (3 papers, 2020 to 2024). An acute or chronic inflammatory process that affects the tissues that surround and support the teeth. "The expression of GPR18 in periodontitis before treatment was significantly higher than in periodontitis after treatment while the expression of GPR32 in periodontitis before treatment was significantly lower than in periodontitis after treatment." (PMID 32670289, 2020). "Interestingly, the expression of GPR18 was upregulated in the RvD2-treated group of rats with periodontitis." (PMID 38542895, 2024). "Furthermore, the expression of GPR18 gene was shown to be significantly higher in the periodontitis prior to SRP group compared to the periodontitis after SRP group (p-value = 0.04), while the expression of GPR32 gene showed the opposite pattern (p-value = 0.04)." (PMID 32670289, 2020). "Previously, we demonstrated that the level of six lipid mediators (5-HETE, 15-HETE, 15(S)-HEPE, 4-HDHA, 7-HDHA, 17-HDHA) and expression of D-series resolvins corresponding receptor genes (GPR18, GPR32) were significantly altered by periodontitis treatment." (PMID 34177951, 2021). "It was found that expression of GPR18 (DRV2) gene was significantly higher in periodontitis subjects prior to nonsurgical therapy, while expression of GPR32 (DRV1) gene was significantly increased after nonsurgical therapy." (PMID 32670289, 2020). "An increase in SPM synthesis activity was noticed in patients with periodontitis before surgical treatment, particularly the increased levels of the D series resolvin pathway markers 4-HDHA, 7-HDHA, and 17-HDHA, as well as their corresponding receptors, in particular GPR18." (PMID 38542895, 2024).
viral infections (3 papers, 2015 to 2024). "Although we observed limited roles in steady-state lymphopoeisis and in antibody responses to virus infections, we found that GPR18 is required for the restoration of small intestine unconventional IELs following bone marrow transplantation." (PMID 26197390, 2015). "Moreover, despite high levels of expression in other cell types within the immune system, GPR18 is dispensable for hematopoietic development and responses to viral infections." (PMID 26197390, 2015). "Compared to cluster 4, cluster 2 cells showed higher expression of SLAMF7, ZEB2, GZMB, GPR18, CD72, PDCD1 (PD1) and CRTAM that are known to be expressed in terminally differentiated effector cells in viral infections and various cancers." (PMID 38501302, 2024).
atherosclerosis (2 papers, 2023 to 2024). A disease characterized by the build-up of fatty material and calcium deposition in the arterial wall resulting in partial or complete occlusion of the arterial lumen. "For instance, Gpr18 and RvD2 were shown to be upregulated in human coronary arteries in presence of atherosclerotic lesions; and the treatment of ApoE-deficient hyperlipidemic mice with the Gpr18 antagonist O-1918 was shown to reduce atherosclerosis." (PMID 37645248, 2023). "This research group showed that the highest expression of GPR18 was observed in the human coronary artery at the early stages of atherosclerosis, which was correlated with a high concentration of RvD2 compared to healthy coronary arteries." (PMID 38542895, 2024). "This could be because the expression of GPR18 is considerably lower in advanced atherosclerosis, which could lead to a decrease in RvD2 function." (PMID 38542895, 2024).
colonic cancer (2 papers, 2014 to 2021). "Another seven-transmembrane G protein-coupled receptor, termed GPR18, was first identified in canine gastric mucosa and a human colonic cancer cell line, with a high abundance of the GPR18 transcript detected in human testis and spleen tissue." (PMID 33652704, 2021).